ALCAM (activated leukocyte cell adhesion molecule)
Diseases named in the same sentence as ALCAM in open-access papers (continued):
Sharing a sentence is not in itself a finding about the gene and the disease.
E. coli infection (1 paper, 2018). "The results suggested that miR-192 and its key target genes (DLG5 and ALCAM) could have a key role in E. coli infection." (PMID 29363554, 2018). "The results suggested that miR-192 and its key target genes (DLG5 and ALCAM) could have a key role in E. coli infection in piglets." (PMID 29363554, 2018).
endothelial dysfunction (1 paper, 2025). In vascular diseases, endothelial dysfunction is a systemic pathological state of the endothelium (the inner lining of blood vessels) and can be broadly defined as an imbalance between vasodilating and vasoconstricting substances produced by (or acting on) the endothelium. "For example, the concurrent elevation of adhesion molecules (ALCAM and VCAM1) alongside pro-inflammatory cytokines (TNFRSF1B and OPN) could provide deeper insights into endothelial dysfunction and immune activation in LN." (PMID 40047601, 2025).
gout (1 paper, 2023). A condition characterized by painful swelling of the joints, which is caused by deposition of urate crystals. "By comparing the information flow between gout flares and remission, we identified that 15 of 42 pathways were highly active during gout flares, including 9 pathways involved in inflammatory and immune responses, such as CCL, IL-16, MHC-II, CLEC, GLAECTIN, ITGB2, and ALCAM." (PMID 38063198, 2023).
Hepatitis (1 paper, 2022). Inflammation of the liver. "The spatial proximity between CD6+CD4+ T cells and ALCAM+ hepatocytes is observed in the interface hepatitis lesion." (PMID 36159854, 2022). "Therefore, increased ALCAM may be involved in the evolution of hepatitis by driving the hepatic enrichment and infiltration of CD6highCD4+ T cells in AIH." (PMID 36159854, 2022).
Hypertension (1 paper, 2016). The presence of chronic increased pressure in the systemic arterial system. "The top gene association from the SKAT analysis, ALCAM, has been identified in a quantitative trait locus for systolic blood pressure in previous literature and has shown differential gene expression in rats with hypertension." (PMID 27980634, 2016).
infertile (1 paper, 2015). "The expression of CD166/ALCAM was significantly higher in the CC-treated group compared with ovulatory and untreated infertile women." (PMID 25981399, 2015).
invasive breast carcinoma (1 paper, 2018). A carcinoma that infiltrates the breast parenchyma. "Serial sections of pathological specimens of invasive breast cancer revealed that Wnt5a was expressed in the cytoplasm, whereas ALCAM was expressed in the plasma membrane." (PMID 29765514, 2018).
liver cirrhosis (1 paper, 2017). "However, ALCAM overexpression was correlated with liver cirrhosis." (PMID 29375378, 2017).
malignant mesothelioma (1 paper, 2020). A malignant neoplasm of the pleura or peritoneum, arising from mesothelial cells. "For example, in cell lines of malignant mesothelioma and endometrioid endometrial cancer, proliferation and migration are inhibited in vitro by ALCAM silencing." (PMID 33270750, 2020).
medullary thyroid cancer (1 paper, 2011). "ALCAM expression in papillary and medullary thyroid cancer specimens and in the surrounding non-tumoral component was studied by western blot and immunohistochemistry, with results demonstrating that tumor cells overexpress ALCAM." (PMID 21364949, 2011).
metabolic syndrome (1 paper, 2013). A cluster of metabolic risk factors for CARDIOVASCULAR DISEASES and TYPE 2 DIABETES MELLITUS. "Interestingly, the expression of some of these genes (C1S, SAA2, ALCAM, CTSB, YKL-40 and tenomodulin) was found to be associated with some relevant metabolic syndrome features." (PMID 23975165, 2013).
myocardial infarction (1 paper, 2022). Gross necrosis of the myocardium, as a result of interruption of the blood supply to the area, as in coronary thrombosis. "Indeed, ALCAM+ cells are known to restore cardiac function after their transplantation in an in vivo rat model of myocardial infarction, these cells are able to generate multiple cell types including cardiomyocytes and endothelial cells." (PMID 35420389, 2022).
pancreatic ductal adenocarcinoma (1 paper, 2020). An infiltrating adenocarcinoma that arises from the epithelial cells of the pancreas. "In addition, a recent study in pancreatic ductal adenocarcinoma has shown that high expression of ALCAM, POU5F1B, and SMO in CTCs is associated with a worse prognosis and with an increase of stemness markers POU5F1B, CD44, and ALCAM 3 months after palliative chemotherapy." (PMID 32192534, 2020).
Pleural effusion (1 paper, 2010). The presence of an excessive amount of fluid in the pleural cavity. "Most cell lines derived from pleural effusions (MB-157, MDA-MB-435, HCC1428, MDA-MB-453, MCF-7, MDA-MB-231 and SK-BR-3) expressed relatively low levels of ALCAM mRNA, while cells originating from the lymph node (HCC70, HCC1008 and BT549) expressed relatively high amounts of ALCAM mRNA." (PMID 20929568, 2010).
pleural mesothelioma (1 paper, 2023). A neoplasm that arises from the mesothelial cells of the pleura. "Although there is very little knowledge on ALCAM in mesothelial cells, the role of ALCAM in mesothelial cell-derived malignancies, namely pleural mesothelioma, has been reported." (PMID 36614319, 2023).
posterior uveitis (1 paper, 2019). Inflammation of the choroid as well as the retina and vitreous body. "The determination of ALCAM’s involvement in these processes is important as ischemic retinal vasculopathies and posterior uveitis have led to vision loss in people in the United States and worldwide." (PMID 30783131, 2019).
retinal degeneration (1 paper, 2018). Degeneration of the retina. "Although the cell adhesion molecule CD166 (also known as ALCAM) is expressed by retinal ganglion cell axons during retinal development, its role during retinal degeneration has yet to be explored and constitutes a valid target for future investigations." (PMID 30176221, 2018).
type 2 diabetic nephropathy (1 paper, 2020). "The role of ALCAM as a biomarker in renal disease was recently reported in type 2 diabetic nephropathy." (PMID 32460901, 2020). "Given the fact that the expression of ALCAM was also increased in type 2 diabetic nephropathy patients’ glomeruli, ALCAM might not be specific to renal disease in SLE." (PMID 32460901, 2020).
urothelial neoplasm (1 paper, 2017). A neoplasm involving a urothelium. "While elevated serum levels of ALCAM have been reported for several non-urothelial neoplasms, high baseline levels of circulating ALCAM prevent its global implementation as a blood-based biomarker." (PMID 27894096, 2017).
tumor (228 papers, 2003 to 2026). "In terms of specific communication signals, tumor-associated ductal cells increase the output of signals such as ALCAM and OCLN and the input of signals such as CD96 and CD6." (PMID 40688078, 2025). "In accordance, Minner et al42 showed that ALCAM overexpression was associated with favorable tumor stage and reduced risk of biochemical recurrence." (PMID 35689436, 2022). "High-grade, ER-positive, and PR-positive tumours tend to be more intensive in staining, and that loss of ALCAM staining was associated with significantly shorter overall and disease-free survival of the patients." (PMID 34680335, 2021). "At the protein level, ALCAM, which was largely confined to the cell membrane, was detected in over 72% of the tumours, and high ALCAM protein levels were linked to a short survival of the patients." (PMID 34680335, 2021). "High levels of ALCAM in primary tumours and in brain metastatic tumour are both associated with poor survival of the patients." (PMID 34680335, 2021). "In human oesophageal squamous cell carcinoma (SCC), tumour tissues were found to have a high degree of staining of ALCAM, which was linked to tumour grade, TNM, and survival." (PMID 34680335, 2021). "It is interesting to note that ALCAM levels are linked to the status of Myc amplification of the tumours." (PMID 34680335, 2021). "Other work has demonstrated that 47% of OSCC tumours stained positive for ALCAM and that the positive staining was linked to a short survival of the patients, appearing to be an independent factor." (PMID 34680335, 2021). "Although membranous staining of ALCAM is linked to tumour staging and shorter overall survival, the cytoplasmic presence of ALCAM protein seems less prominent in the relationship with clinical outcome and survival of the patients." (PMID 34680335, 2021). "The attenuation of ALCAM enhances the invasive abilities of the tumor, which is arguably caused by the reduction of ALCAM-mediated adhesion, resulting in less adhesive and more mobile tumor cells." (PMID 33270750, 2020). "Patients with tumors with high ALCAM expression had greater risk of tumor recurrence one year after surgery." (PMID 29463803, 2018). "Consistent with the results of previous study, our study also showed that the level of the ALCAM gene methylation is associated with the levels of ALCAM transcripts in tumor tissues." (PMID 29315254, 2018). "As previously noted, changes in total mRNA expression rarely correlate with the changes in protein expression in tumor tissues, therefore suggesting that ALCAM shedding is the likely cause for these discrepancies reported in the literature." (PMID 29453336, 2018). "In this study, we go further in our understanding of ALCAM in EC tumorigenesis by evaluating its full-form expression in two different areas of the tumor and its relation with key molecules associated to the epithelial and mesenchymal context." (PMID 29682175, 2018). "Detection of shed ALCAM in tumor-adjacent fluids makes it a promising non-invasive and cost-effective biomarker in BCa as well as other cancers with tumor-associated biofluids." (PMID 27894096, 2017). "We identified only one gene differentially expressed between high-grade and low-grade tumor epithelium, ALCAM, a TGFβ responsive gene, previously shown to be associated with metastasis." (PMID 28871082, 2017). "Analysis of 5 studies with 1826 cases that reported significance of ALCAM expression to tumor grade revealed that ALCAM overexpression was associated with the higher tumor grade (HR = 1.28, 95%CI = 1.00–1.62, P = 0.05)." (PMID 28537909, 2017). "This points to the in vivo existence of a causal molecular connection between FSTL1 and ALCAM within the tumor microenvironment in patients." (PMID 25883937, 2015). "ALCAM has been identified as a marker of metastasis in many tumor cell types, and yet in other cases it has been associated with inhibition of metastasis." (PMID 22745734, 2012).
tumor (continued). "In order to determine the association of elevated s-ALCAM levels with patient survival and tumor stage, different statistical analyses were performed." (PMID 22745698, 2012). "In untreated patients, ALCAM overexpression in tumor tissue tended to be associated with shorter cancer-specific survival (CSS) and disease-free survival (DFS)." (PMID 22475274, 2012). "Other work has shown that an antibody to ALCAM can recognise well endothelial cells surrounding metastatic tumours of the brain, indicating a cell-based targeting possibility, namely targeting tumour-associated endothelium." (PMID 34680335, 2021). "However, tumour tissues were found to have high levels of ALCAM protein and transcript, and the high levels were associated with shorter survival of the patients." (PMID 34680335, 2021). "In addition, high ALCAM levels are associated with poor survival, early tumor relapse and chemoresistance." (PMID 31552188, 2019). "Tumor relapse, as poor risk factors were associated with ALCAM." (PMID 29463803, 2018). "The ALCAM gene methylation was associated with the ALCAM transcripts in tumor tissues." (PMID 29315254, 2018). "The level of ALCAM transcripts was positively associated with the expression of tumor necrosis factor α (TNFα), nuclear factor-kappa B (NF-κB) p50 subunit, and interleukin (IL)-4 in tumor tissues (p < 0.001, p < 0.001 and p = 0.012, respectively)." (PMID 29315254, 2018). "Interestingly, loss of membranous E-cadherin/β-catenin and increased cytoplasmic ALCAM expression was significantly associated in OSCCs and correlated with aggressive tumor behavior (enhanced tumor invasiveness, late clinical stage, and nodal metastasis)." (PMID 23840677, 2013). "On the basis of these data, ALCAM overexpression in neoplastic thyroid tissues, analogously to other tumor types, could be implicated in tumor invasiveness and dedifferentiation processes." (PMID 21364949, 2011). "Our data suggests that loss of ALCAM expression, due in part to DNA methylation of extensive segments of the promoter, significantly impairs the ability of circulating tumor cells to adhere to each other, and may therefore promote metastasis." (PMID 20929568, 2010). "Additionally, vaccine-induced cytotoxic T-lymphocytes can recognize an epitope expressed by ALCAM and this could be useful as a novel mechanism of induction of potent tumor-specific cellular responses by mimotopes of tumor-associated carbohydrate antigens." (PMID 32085563, 2020). "Thus, the expression of CHL1, NrCAM, L1CAM, and ALCAM may be associated with a less aggressive tumor and, as a consequence, with a better prognosis." (PMID 31989042, 2019). "We hypothesized that a bispecific composed of an anti-effector (e.g., anti-LRP6) antibody and an antibody binding to a guide antigen (e.g., a tumor-associated cell surface molecule such as ALCAM, EphA2 or ICAM-1) will modulate potency and cell type selectivity of the anti-effector antibody." (PMID 29335534, 2018). "Another stem cell marker is CD166 (ALCAM), a type-1 glycoprotein belonging to the immunoglobulin superfamily, recognized for its role in the maintenance of CSCs’ characteristics, such as tumor initiation, growth and invasion." (PMID 40564019, 2025). "Previous studies have suggested that ALCAM is closely related to tumor-infiltrating immune cells and tumor immunotherapy." (PMID 40118855, 2025). "Conventional type 1 dendritic cells (cDC1) were key regulatory factors in anti-tumor T cell responses, and ALCAM-mediated interactions between cDC1-CD8 T cells were inhibited in advanced lung tumors." (PMID 40118855, 2025). "Since it is established that CD6 ligands ALCAM and CD318 levels are increased in malignant tumors, expression levels of CD6, CD318, and ALCAM were assessed on five human tumor cell lines: MDA-MB-231, MCF-7, NCI-H460, HCT-116, and SKOV-3." (PMID 40391211, 2025).
tumor (continued). "Both ALCAMhigh macrophages and Tex tend to be enriched at the tumor boundary and hypoxia can induce the expression of ALCAM in macrophages." (PMID 38956900, 2024). "ALCAM-mediated tumour-mesothelial interaction leads to settling of cancer cells over the peritoneum, a process likely to require the participation of the SRC kinase signaling." (PMID 36614319, 2023). "In vitro experiments showed that deleting ALCAM expression through CRISPR/Cas9 technology reduces tumor cell adhesion to the BE, subsequently decreasing the ability of tumor cells to extravasate through the BBB." (PMID 37190188, 2023). "Patients who had tumours with high levels of ALCAM had a much shorter peritoneal metastasis free survival compared with those who had low ALCAM expression (p = 0.006)." (PMID 36614319, 2023). "Here, we have demonstrated that using a soluble form of ALCAM (sALCAM), the interaction between tumour cells and mesothelial cells was disrupted." (PMID 36614319, 2023). "To validate the potential promoting role of ALCAM in terms of peritoneal metastasis, we created ALCAM-manipulated cell models in both cancer cells and mesothelial cells to explore the tumour-mesothelial cell interaction in vitro." (PMID 36614319, 2023). "With the findings from the dynamic interaction between tumour and mesothelial cells being mediated by ALCAM expression, we employed an end point analysis of tumour interactions by visualising this interaction at the end of the experiments." (PMID 36614319, 2023). "These cell models were used in the tumour-mesothelial interaction assay to assess if and how the interaction was influenced by ALCAM." (PMID 36614319, 2023). "The impact of ALCAM expression in these tumours was also correlated to the patients’ clinical outcomes, namely peritoneal metastasis-free survival." (PMID 36614319, 2023). "At this stage, the circulating cancer cells (seeds) would utilize the surface ALCAM to identify its homotypical partner on mesothelial cells and find the time and condition to settle over the peritoneum and form peritoneal surface tumours." (PMID 36614319, 2023). "Blocking VLA-4-1 and ALCAM expressed on tumor cells was shown to significantly reduce BM through decreasing tumor cell adhesion and subsequent extravasation across the BE." (PMID 37190188, 2023). "On the other hand, full-length transmembrane ALCAM was found on tumor-derived peritoneal EVs in OvC, although the involvement of this exosomal ALCAM in the pathology of OvC has not been established." (PMID 35628559, 2022). "Of note, tumor cells from ORs and SORs were the most prominent sources of ALCAM on effector T cells and BAG6 on NK cells, respectively." (PMID 36380017, 2022). "CD166 (also known as activated leukocyte cell adhesion molecule, or ALCAM) is a transmembrane immunoglobulin that has been reported to take part in resistance to therapies in cancer, contributing to tumour propagation and invasiveness." (PMID 36077593, 2022). "ALCAM has previously been utilized to evaluate tumor invasiveness and immunity; however, it has received little attention in AD research." (PMID 36685605, 2022). "CRC stem cells characterized by the expression of markers such as ALCAM have been reported to harbor tumor-initiating and highly proliferative potential in tumor xenograft models." (PMID 35328677, 2022). "The observation that the levels of soluble ALCAM in the uterine aspirate fluids of the patients correlated well with MMP9 staining in tumour tissues indicated the possibility of ALCAM shedding from tumours by the metalloproteinases." (PMID 34680335, 2021). "This is partly reflected by an in vivo investigation where reduction in ALCAM by selenoglycoprotein would render a greatly reduced presence of metastatic tumour cells in the brain and reduction in brain metastasis." (PMID 34680335, 2021). "Together with chemotherapy and tumour staging, ALCAM appears to be an independent survival indicator of the patients." (PMID 34680335, 2021).